FSCN1 (fascin actin-bundling protein 1)
Diseases named in the same sentence as FSCN1 in open-access papers (continued):
Sharing a sentence is not in itself a finding about the gene and the disease.
bladder cancer (30 papers, 2010 to 2025). "Recent studies have shown an association between the up-regulated expression of FSCN1 and increased invasiveness of carcinomas in the urinary bladder, which suggests that FSCN1 may be a marker of aggressive bladder cancer." (PMID 33853613, 2021). "Luciferase assays confirmed that miR-145 directly binds to FSCN1 mRNA, resulting in the inhibition of both FSCN1 mRNA and protein expression, which in turn inhibits bladder cancer cell growth, invasion, and migration." (PMID 40689207, 2025). "In bladder cancer, overexpression of FSCN1 increases cell migration and promotes metastasis, correlating with increased risk of progression and predicting invasiveness and recurrence." (PMID 34737886, 2021). "In esophageal squamous cell carcinoma and bladder cancer, miR-133a targets fascin actin-bundling protein 1 (FSCN1) to regulate cancer cell invasion, migration and proliferation." (PMID 27825300, 2016). "More interesting, FSCN1 has been verified as the target of miR-145 in bladder cancer, esophageal squamous cell carcinoma, and prostate cancer." (PMID 25816323, 2015). "FSCN1 has been proven to be a metastatic gene and target of miR-133a in esophageal squamous cell carcinoma and bladder cancer." (PMID 25104873, 2014). "In molecular studies, miR-133a has been shown to directly regulate several metastasis-related oncogenes, including FSCN1 in bladder cancer, LASP1 in CRC, and CAV1 in head and neck squamous cell carcinoma." (PMID 25104873, 2014). "MiR-133a targets FSCN1 in bladder cancer and CAV1 in head and neck squamous cell carcinoma functioning as a tumor suppressor." (PMID 25104873, 2014). "In bladder cancer, miR-145 also directly targets FSCN1 and inhibits bladder cancer cell line growth, migration and invasion significantly." (PMID 24026105, 2013). "FSCN1 plays a critical role in regulating the migration and invasion of bladder cancer cells." (PMID 40689207, 2025). "It has been demonstrated that the overexpression of miR-145 could reduce bladder cancer migration through regulating FSCN1." (PMID 35602576, 2022). "In addition, UCA1 promotes migration and invasion of bladder cancer cells via the has-miR-145/ZEB1/2/FSCN1 pathway." (PMID 34238213, 2021). "Fascin 1 (FSCN1) promotes progression of bladder cancer and non-small cell lung cancer cells." (PMID 34016787, 2021). "Fascin-1 (FSCN1) plays an important role in the regulation of cellular migration and invasion during tumor progression, but how its regulatory mechanism works through the ceRNA effect is still unclear in bladder cancer (BLCA)." (PMID 30823924, 2019). "Furthermore, miR145 and miR133a decreased bladder cancer aggressiveness by targeting fascin actin-bundling protein 1 (FSCN1), which binds β-catenin to increase motility and invasion." (PMID 27036026, 2016). "For instance, circPTPRA suppressed bladder cancer growth and metastasis via downregulation of m6A-modified MYC proto-oncogene, bHLH transcription factor (MYC) and fascin actin-bundling protein 1 (FSCN1) through interacting with IGF2BP1." (PMID 37370759, 2023). "In bladder cancer, this RBP usually promotes tumor proliferation, migration, and invasion by regulating the expression of MYC and FSCN1." (PMID 37835380, 2023). "It enhances bladder cancer cell migration and invasion in part though hsa-miR-145/ZEB1/2/FSCN1 pathway." (PMID 27326854, 2016). "In bladder cancer, ZEB1-AS1 regulated FSCN1 expression through miR-200b sponges." (PMID 38077434, 2023). "As previous studies have reported, miR-145-5p could repress the progression of bladder cancer by regulating SOX11; further, miR-145-5p could suppress the progression of laryngeal squamous cell carcinoma via FSCN1." (PMID 32706759, 2020). "lncRNA-UCA1 induces EMT in bladder cancer cells by up-regulating the expression levels of zinc-finger E-box-binding homology boxes 1 and 2 (ZEB1 and ZEB2), and it regulates bladder cancer cell EMT through the tumor suppressor hsa-miR-145 and its target gene FSCN1." (PMID 40689207, 2025).
bladder cancer (continued). "Meanwhile, for GO enrichment analysis for down regulated genes, genes such as GSN, FSCN1, and PHLDB2 were important for the invasion of many cancer types such as pancreatic cancer, bladder cancer, and colon cancer cells, but these genes may be involved in the invasion of GBM." (PMID 31137733, 2019).
esophageal squamous cell carcinoma (28 papers, 2012 to 2026). Esophageal squamous cell carcinoma (ESCC) is a type of esophageal carcinoma (EC) that can affect any part of the esophagus, but is usually located in the upper or middle third. "LINC01711, a competitive endogenous RNA, has been found to be closely linked to the proliferation, migration, and invasion of esophageal squamous cell carcinoma via suppressed miR-326 and facilitated the level of FSCN1." (PMID 36118856, 2022). "Recent evidence showed that the cluster of miR-143 and miR-145 affected the risk of esophageal squamous cell carcinoma through regulating oncogenic Fascin Homolog 1 (FSCN1)." (PMID 22970328, 2012). "Exosomal lncRNA LINC01711 been shown to promote the metastasis of esophageal squamous cell carcinoma through the miR‐326/FSCN1 axis." (PMID 38043920, 2024). "Previous studies identified KLF4 as a target of miR-145-5p in human embryonic stem cells and FSCN1 as a target of miR-143-3p in esophageal squamous cell carcinoma." (PMID 38866991, 2024). "In esophageal squamous cell carcinoma, FSCN1 was reported to promote tumor progression by the AKT/GSK3β signaling pathway." (PMID 37491232, 2023). "Among the lncRNAs included in the signature, LncRNA LINC01711 was demonstrated to promote the occurrence and development of esophageal squamous cell carcinoma through increasing cell proliferation, migration, and invasion by the miR-326/FSCN1 axis." (PMID 36105083, 2022). "miR-133b has been reported to directly target oncogenic FSCN1 gene in esophageal squamous cell carcinoma." (PMID 25433493, 2014). "miR-133b has been reported to directly target oncogenic Fascin actin-bundling protein 1 (FSCN1) in esophageal squamous cell carcinoma." (PMID 25433493, 2014). "For example, miR-145 has been found to inhibit cancer cell growth, invasion, and metastasis by suppressing EGFR and NUDT1 in lung adenocarcinoma, FSCN-1 in esophageal squamous cell carcinoma, N-cadherin in gastric carcinoma, and IGF in hepatocellular carcinoma." (PMID 26514209, 2015). "miR-133b has been reported to directly regulate FSCN1 in esophageal squamous cell carcinoma." (PMID 25433493, 2014). "MiR-133a and miR-133b have been shown to both target FSCN1 in esophageal squamous cell carcinoma that could potentially be mirrored in CRC as they share several other potential target genes due to their high similarity in sequence, that is, only differing by one nucleotide." (PMID 25104873, 2014). "Through its interaction with miR-326 and FSCN1, LINC01711 has been shown to promote esophageal squamous cell carcinoma initiation and progression." (PMID 36874011, 2023). "In esophageal squamous cell carcinoma (ESCC), overexpression of miR-133a decreased invadopodia formation-related protein FSCN1 and MMP14 levels." (PMID 34290983, 2021). "Among them the Src family member YES1 has been reported as a direct miR-145 target that plays oncogenic function in colon cancer, FSCN1 and PPP3CA are also directly regulated by this miRNA in esophageal squamous cell carcinoma and urothelial carcinoma." (PMID 25069957, 2014). "FSCN1 expression is absent or low in normal epithelia, but FSCN1 is overexpressed in many carcinomas, including colorectal adenomas, epithelial ovarian cancer and esophageal squamous cell carcinoma." (PMID 26010149, 2015). "In oesophageal squamous cell carcinoma (ESCC) cells, KAT8 catalyzed the acetylation of fascin actin-bundling protein 1 (FSCN1) at lysine 41, enhancing its F-actin-bundling activity and promoting filopodia/invadopodia formation to drive ESCC cell invasion." (PMID 40508066, 2025). "Moreover, in esophageal squamous cell carcinoma, overexpression of the epidermal growth factor (EGF) increased specificity of protein 1 (Sp1) phosphorylation and activated the ERK1/2 pathway, thus enhancing FSCN1 expression." (PMID 34830909, 2021).
prostate carcinoma (20 papers, 2013 to 2025). A carcinoma that arises from epithelial cells of the prostate gland. "Here we investigated the expression and functional significance of Fascin-1 (FSCN1), a pro-metastasis actin-bundling protein associated with poor prognosis of several cancers, in neuroendocrine differentiation of prostate cancer." (PMID 37875732, 2023). "Another study showed that lncRNA-PCAT1 contributes to prostate cancer risk by regulating FSCN1 via miR-145-5p." (PMID 31464517, 2019). "FSCN1 is associated with the progression of prostate cancer, while malic acid (or ionized malate) is an intermediate involved in glutamine metabolism pathways that play major roles in cancer metastasis." (PMID 29506475, 2018). "Notably, FSCN1 associated with taxane-resistant expressed highly in single-cell subclonal populations in ARLow/mCRPC/NEPC prostate cancer (PC3, PC3M, and DU145)." (PMID 37476073, 2023). "Further studies are required to evaluate a possible diagnostic role of FSCN1 in prostate cancer." (PMID 34737886, 2021). "The aberrant upregulation of FSCN1 protein consequently promotes the proliferation of prostate cancer cells while inhibiting apoptosis." (PMID 40689207, 2025). "We demonstrated that FSCN1 is upregulated during neuroendocrine differentiation of prostate cancer in vitro, leading to phenotypic changes and NEPC marker expression." (PMID 37875732, 2023). "Recent studies identified FSCN1 as a taxane-resistant marker in several solid tumors, including prostate cancer." (PMID 37476073, 2023). "We identified FSCN1 as a key upregulated gene (4.71-fold) for taxane resistance in aggressive prostate cancer." (PMID 37476073, 2023). "FSCN1 is a potential novel biomarker that we investigated in patients with prostate cancer and evaluated in serum through a quantitative assay." (PMID 34737886, 2021). "For example, silencing the lncRNA, CCAT1, decreases paclitaxel resistance in prostate cancer by upregulating miR-24-3p and decreasing FSCN1 levels." (PMID 34511042, 2021). "LncRNA PCAT-1 contributes to prostate cancer tumorigenesis through modulating FSCN1 and sponging miR-145-5p." (PMID 32781986, 2020). "MiR-145 participates in the modulation of proliferation and invasion by targeting FSCN1 in various cancers, including bladder cancer, oesophageal squamous cell carcinoma, prostate cancer, melanoma cells and breast cancer cells 91,133–138." (PMID 25124875, 2014). "Restoration of miRNA-145 suppresses prostate cancer cell proliferation, migration and invasion by targeting FSCN1." (PMID 25436889, 2014). "Consequently, miR-145 inhibits cell proliferation, migration, and invasion in prostate cancer by targeting FSCN1." (PMID 40689207, 2025). "Importantly, the taxane-resistant gene FSCN1 was also identified as a common gene in both cohorts of prostate cancer cell lines." (PMID 37476073, 2023). "Moreover, the taxane-resistant gene FSCN1 was also found to be a common gene in both cohorts of prostate cancer cell line models." (PMID 37476073, 2023). "In human prostate cancer samples, FSCN1 expression is restricted to NEPC tumours." (PMID 37875732, 2023). "Moreover, miR-145 inhibits cell proliferation, migration, and invasion by targeting FSCN1 in prostate cancer." (PMID 35711849, 2022). "Thus, miRNA-24 targets FSCN1 in nasopharyngeal and prostate cancer, FSCN1 is targeted by miRNA-143 in esophageal and miRNA-326 in lung and gastric cancers, respectively." (PMID 34830909, 2021). "A recent study has revealed that FSCN1 enhances paclitaxel resistance in prostate cancer." (PMID 33614909, 2021). "Similar to FSCN1, another actin-binding protein, the SWAP switching B-cell complex 70 kD subunit (SWAP70), was confirmed as a target of miR-145, which is associated with miR-145's modulation of cell migration and invasion in prostate cancer." (PMID 25124875, 2014).
prostate carcinoma (continued). ",93,158,160, 161, 162, 163, 164 Furthermore, the FSCN1 gene has been identified as a direct target of several miRNAs, such as miR-143 in chondrosarcoma and esophageal carcinoma, miR-24 in nasopharyngeal and prostate cancer, miR-326 in lung and gastric cancer, and so on." (PMID 33614909, 2021). "Fascin actin-bundling protein-1/FSCN1, a taxane-resistant gene, was identified as a top DEG among all prostate cancer subtypes." (PMID 37476073, 2023). "PCAT1 promotes prostate cancer proliferation through c-MYC via sponging miR-3667-3p and FSCN1 via sponging miR-145-5p." (PMID 35075375, 2022). "Downregulation of FSCN1 expression in prostate cancer cells DU14510 or renal cancer cells 786-O120 was shown to suppress tumor metastases in nude mice, whereas the overexpression of FSCN1 in osteosarcoma SaOS-2 cells enhanced lung metastasis in severe combined immunodeficiency (SCID) mice." (PMID 33614909, 2021). "The analysis of FSCN1 using immunohistochemistry in prostate carcinoma glands found that only 8% of PCa had more than 10% FSCN1 positivity; FSCN1 expression, however, did not correlate with Gleason score, tumor stage, serum PSA levels or biochemical relapse following surgery." (PMID 34737886, 2021).
colorectal cancer (17 papers, 2016 to 2025). A primary or metastatic malignant neoplasm that affects the colon or rectum. "Based on a systematic review and meta-analysis, high FSCN1 expression is associated with an increased risk of progression in colorectal, breast and esophageal cancer and with the presence of metastatic lesions in gastric and colorectal cancer." (PMID 37634036, 2024). "A systematic review and meta-analysis of studies analyzing the relevance of FSCN1 in five different carcinomas (breast, colorectal, esophageal, gastric, and lung) by IHC reported that FSCN1 correlates with a high risk of disease progression in breast and colorectal cancers." (PMID 34830909, 2021). "Lyar also interacts with the promoter region of Fscn1 to promote its expression, modulating the downstream fatty acid metabolism in colorectal cancer cells." (PMID 40408479, 2025). "Lyar directly interacts with the promoter region of Fscn1 to up-regulate its expression, thereby affecting the downstream fatty acid metabolism in colorectal cancer cells." (PMID 40408479, 2025). "It has been demonstrated that the FSCN1 gene is a direct downstream target of the Wnt/β-catenin signaling pathway in colorectal cancer cells." (PMID 35711849, 2022). "It has recently been established that LINC00152 regulates FSCN1 by sponging with miR-632 and miR-185-3p in colorectal cancer." (PMID 33614909, 2021). "The association of HPV with FSCN1 was also reported by our group, where we demonstrated that E6/E7 oncoproteins of HPV is associated with FSCN1 overexpression in human colorectal cancer." (PMID 34830909, 2021). "In colorectal cancer, upregulated FSCN1 expression was reported in LMP1-positive samples and was associated with moderately to poorly differentiated adenocarcinomas." (PMID 34830909, 2021). "Multiple downstream targets including vimentin and FSCN1 have been identified to mediate EMT induced by TEAD4 in colorectal cancer and gastric cancer." (PMID 30459528, 2018). "This suggested that LYAR regulates FSCN1 expression in only a subset of colorectal cancers." (PMID 35069968, 2021). "Here, a Yes‐associated protein 1 (YAP1) target lncRNA LINC00152 is identified, and a critical role of YAP1/LINC00152/FSCN1 axis in the tumorigenesis of colorectal cancer (CRC) is revealed, which may provide a potential new target for CRC diagnosis and therapy." (PMID 32042551, 2020). "Additionally, we showed that interfering with miR-145-5p or overexpressing FSCN1 could reverse the effect of silencing PTOV1-AS2 on the biological function of colorectal cancer cells." (PMID 36960218, 2023). "Forced expression of FSCN1 in cultured colorectal cancer cells promoted their migratory and invasive capabilities in vitro and enabled cells had higher abilities to form metastases in vivo, whereas specific inhibition of FSCN1 expression reduced colorectal cancer cells invasion." (PMID 33753991, 2021). "As LASP1 forms complexes with FSCN1 to serve as indispensable actin filament-bundling proteins that stabilize the lamellipodia of cancer cells and has already been demonstrated to promote the metastasis of colorectal cancer, we predicted that LASP1 is another potential target of miR-145." (PMID 27626692, 2016). "In colorectal cancer (CRC) specifically, miR-133 has been reported to target multiple oncogenic factors including LASP1, TAGLN2, FSCN1, and COL1A1, thereby suppressing proliferation, migration, and invasion." (PMID 41300774, 2025). "In addition to migrastatin, another investigation in colorectal cancer cells showed an antimigratory and anti-invasive effect of imipramine (anti-depressant) by inhibiting FSCN1 activity, thus introducing a novel molecular targeted treatment in FSCN1-induced tumors." (PMID 34830909, 2021).
colorectal cancer (continued). "Further knockdown experiments using colorectal cancer cells revealed invasion or migration promoting roles for SPARC, FN1 and FSCN1." (PMID 30473751, 2018). "In colorectal cancer, the β-catenin-TCF signaling pathway was reported to regulate FSCN1 transcription; however, the studies in breast and colon cancer failed to report the regulation of FSCN1 expression via β-catenin-TCF signaling." (PMID 34830909, 2021).